FTO (FTO alpha-ketoglutarate dependent dioxygenase)
Diseases named in the same sentence as FTO in open-access papers (continued):
Sharing a sentence is not in itself a finding about the gene and the disease.
cancer (continued). "To answer this, we plotted the dependency of cell lines on FTO across all 1183 cancer cell lines using both the CRISPR and RNAi datasets." (PMID 41279954, 2025). "Various roles of FTO‐mediated m6A demethylation in the development of cancer progression has emerged in recent years." (PMID 40022434, 2025). "Among these, FTO-43N emerged as a lead compound, effectively elevating m6A and m6Am levels in gastric cancer cells, ultimately exerting anti-cancer effects by regulating the Wnt/PI3K-Akt signaling pathway." (PMID 40823087, 2025). "In cancer stem cells, studies have shown that the depletion of FTO and ALKBH5 leads to increased m6A modification, which can significantly reduce the self-renewal ability of cancer stem cells." (PMID 40356596, 2025). "Emerging recent evidence has revealed the essential function of FTO in promoting tumorigenesis, and FTO can serve as a potential cancer therapeutic target." (PMID 40234389, 2025). "The results of the bioinformatics analysis confirmed the positive correlation between TTC7B and FTO transcripts in both normal and cancer tissues of the gut." (PMID 39897037, 2025). "FTO has emerged as a potential biomarker in cancer research due to its critical role in RNA epigenetics, particularly in regulating m6A demethylation." (PMID 39820532, 2025). "A variety of FTO-targeted inhibitors have been developed, including MO-I-500, meclofenamic acid (MA), FB23, R-2HG, and rhodopsin, which significantly inhibit the proliferation of cancer cells by inhibiting the enzymatic activity of FTO." (PMID 40458727, 2025). "Although FTO has been identified to be overexpressed and oncogenic in various cancers, it is expressed in most tissues and play roles in regulating metabolism and energy homeostasis." (PMID 40815637, 2025). "Invasion and stemness are crucial for cancer cell migration and metastasis, and FTO enhances EC cell migration and invasion." (PMID 39802639, 2025). "Some studies have related FTO SNPs with various types of cancer, including BC, where the overexpression of FTO promotes cell glycolysis and impacts the PI3K/Akt signaling pathway." (PMID 40149317, 2025). "As the first discovered RNA m6A demethylase, FTO is often dysregulated and plays important roles in various types of cancer." (PMID 39351597, 2024). "Recent studies have shown that CS1 and CS2, two newly identified inhibitors of FTO, have a more significant effect in reducing cancer cell viability compared to FB23 and FB23-2." (PMID 39033180, 2024). "Understanding the role of FTO in cancer progression is crucial for developing effective strategies to diagnose and treat GC." (PMID 38956367, 2024). "Functional, the terms of cancer cell growth and metastasis related was enriched in FTO regulated DEGs." (PMID 38200441, 2024). "Targeting m6A‐related enzymes, such as METTL3 and FTO, can effectively inhibit cancer cell growth and proliferation." (PMID 39445003, 2024). "The influence of FTO on cancer metabolism is notable, as it affects the expression levels of HK2 both at the mRNA and protein levels." (PMID 39175477, 2024). "Initially, we conducted an analysis of FTO’s expression across various cancers utilizing the GEPIA database." (PMID 39449798, 2024). "FTO is overexpressed in many cancers and has obvious impacts on the development of cancers, by regulating mRNA splicing, stability, and translation." (PMID 38956367, 2024). "Research on these inhibitors lays a crucial foundation for developing FTO-targeted anti-cancer therapies." (PMID 39192357, 2024). "As the first characterized m6A demethylase, FTO has been reported to regulate the tumorigenesis of different types of cancers." (PMID 38491196, 2024). "As an m6A demethylase, FTO has a carcinogenic effect in a variety of human malignant tumors such as lung cancer and colon cancer, and enhances the proliferation and invasion of cancer cells." (PMID 38166832, 2024).
cancer (continued). "FTO is a crucial factor that contributes to chemotherapy resistance in a variety of cancers; however, its mechanisms vary depending on the cancer type and specific molecular pathways involved." (PMID 39295930, 2024). "We postulate that the targets of FTO in different cancer models vary and determine the its functional identity." (PMID 39268470, 2024). "Our findings underscored the significant contribution of FTO in GC and its promising therapeutic potential for cancer treatment." (PMID 38556586, 2024). "Elevated FTO expression in GC tissues correlates with increased expression of factors promoting cancer development, such as HDAC3 and MYC, while the transcription factor FOXA2 expression decreases." (PMID 39192357, 2024). "Here, we show that shRNA-mediated depletion of ALKBH5 or FTO (using a lentiviral system) significantly decreased ATF4 protein levels in SOR-treated Hep3B cancer cells." (PMID 39199320, 2024). "Upregulated FTO, in turn, can inhibit autophagy, thus forming a positive feedback loop to maintain FTO accumulation and amplify its role in inducing malignant tumors." (PMID 39468015, 2024). "Small-molecule inhibitors targeting FTO have been considered to have potential therapeutic effects in the field of cancer treatment." (PMID 38365891, 2024). "Fat mass and obesity-associated protein (FTO) was the first eukaryotic m6A demethyltransferase to be discovered, and its involvement in adipogenesis and cancer has been linked to its m6A demethylase function." (PMID 38384328, 2024). "For example, the application of IDH inhibitors and FTO inhibitors has demonstrated efficacy in treating patients with IDH mutant cancers." (PMID 39449798, 2024). "Its involvement in key pathways like PI3K/Akt/mTOR and its regulation of oncogenes such as MYC and β-catenin further emphasize the importance of context when evaluating FTO’s function in various cancer types." (PMID 39744011, 2024). "For the effective direction of therapeutic interventions, a thorough comprehension of the FTO’s role in various cancer types or subtypes is paramount." (PMID 39449798, 2024). "The FTO gene codes for a protein that is part of the methylosome complex and has a regulatory role in cancer development." (PMID 39040764, 2024). "Another recent study reported that FTO-induced upregulation of flotillin-2 contributed to cancer aggressivness in diffuse large B-cell lymphoma by activating PI3K/Akt/mTOR pathway." (PMID 39744011, 2024). "FTO acts as an oncogene in certain cancers by altering the m6A modification of crucial transcripts, thereby promoting cancer progression." (PMID 39192357, 2024). "Given the scarcity of research concerning FTO’s involvement in OS, our subsequent investigation focused on elucidating the role of FTO in this specific type of cancer." (PMID 39449798, 2024). "Collectively, these findings highlight the multifaceted role of FTO in the intricate landscape of cancer progression and its potential as a therapeutic target for various malignancies." (PMID 39295930, 2024). "The recent discovery of FTO as an active posttranscriptional RNA modifier has provided additional insight into the regulatory role of genes in cancer." (PMID 39040764, 2024). "Overall, FTO inhibitors are a promising new class of cancer therapeutics, requiring further research and clinical validation for their full potential." (PMID 39192357, 2024). "FTO had been widely studied in various cancers and reported to play crucial roles in the regulation of tumorigenesis." (PMID 38600610, 2024). "Research has shown that FTO is involved in critical processes, such as malignant tumor development, immunosuppression, glycolysis, drug resistance, angiogenesis, epithelial-mesenchymal transition, metastasis, and cancer cell proliferation." (PMID 39175477, 2024).
cancer (continued). "Augmentation of FTO facilitates transition from epithelial to mesenchymal and chemotherapy resistance in cancer cells by lowering m6A levels and improving ZEB1 transcript stabilization and activation." (PMID 38125749, 2023). "Meanwhile, meclofenamic acid (MA), a nonsteroidal anti-inflammatory agent, was identified to specifically inhibit FTO by competitively binding to FTO sites of m6A-modified oncogenic mRNAs, thus effectively suppressing the cancer cell proliferation." (PMID 37015927, 2023). "Then here in current study we evaluated the potential anti‐cancer properties of the entacapone as FTO inhibitor in ESCC cells." (PMID 36534072, 2023). "Inspired by this discovery, researchers have reported an increasing number of FTO inhibitors, confirming that FTO is a drug-treatable cancer target." (PMID 37055798, 2023). "Recent studies demonstrated that FTO is overexpressed and plays oncogenic roles in various cancers such as acute myeloid leukemia, gastric cancer, breast cancer, melanoma, and cervical cancer." (PMID 36874096, 2023). "Studies have shown that FTO plays a key role in the self-renewal and immune evasion of CSCs and indicates the great prospects of cancer therapy by targeting FTO." (PMID 37466793, 2023). "Over ten FTO‐targeted small molecule inhibitors were developed against cancers, such as Rhein, meclofenamic acid, quercetin, entacapone, FB23 and FB23‐2." (PMID 36260366, 2023). "Various research groups are now elucidating the molecular involvement of FTO in cancer in terms of its m6A demethylase activity." (PMID 37605223, 2023). "Meclofenamic acid specifically inhibits FTO by competitively binding to FTO sites of m6A-modified oncogenic mRNAs, thus effectively inhibiting cancer cell proliferation." (PMID 37714846, 2023). "RNA demethylase inhibitors have been used in several experimental models and preclinical studies and demonstrate that FTO can work as a potential drug target against cancers." (PMID 37175660, 2023). "In NSCLC, FTO facilitates cancer cell proliferation by activating KRAS signaling or the upregulation of MZF1 or USP7 in an m6A-dependent way." (PMID 37007161, 2023). "m6A modification in mRNA by FTO affects mRNA processing, stability, and translation, and dysregulation of FTO is seen in many types of cancer." (PMID 37007161, 2023). "Because METTL3 or FTO plays an important oncogenic role in many cancers, considerable efforts have gone into developing small-molecule inhibitors that specifically target METTL3 or FTO for cancer treatment." (PMID 39872957, 2023). "In EOC, the nuclear localization of FTO increases and then enhances cancer progress via the mTOR signaling pathway." (PMID 36260366, 2023). "More importantly, FTO was also found to be positively correlated with cancer glycolysis through bioinformatics analysis." (PMID 37840133, 2023). "Increased expression of FTO as m6A demethylase has an oncogenic role in various types of cancers including ESCC." (PMID 36534072, 2023). "Finding HIF-independent anti-cancer targets becomes essential, while FTO is a potential anti-cancer HIF independent target for ccRCC." (PMID 37865763, 2023). "Nevertheless, the involvement of FTO as an m6A demethylase in cancer progression has only recently been discovered." (PMID 36718644, 2023). "Identified as the first RNA m6A demethylase, FTO has been reported to play critical roles in numerous types of cancers." (PMID 37915103, 2023). "Given the critical oncogenic role of RNA demethylases in many types of cancers, the study of FTO and its relevant products has attracted extensive interest." (PMID 37175660, 2023). "FTO firstly recognized to be a regulator in obesity and diabetes, performances different functions in cancers." (PMID 37598390, 2023). "In particular, CS2 is the latest generation of FTO inhibitor, which showed high potency on FTO inhibition and promising anti-cancer effect." (PMID 37365312, 2023).
cancer (continued). "Nafamostat mesylate (NM), a previously discovered serine protease inhibitor used for the treatment of pancreatitis and cancers, was recently identified as a competitive or allosteric FTO inhibitor (IC50 = 13.77 μM)." (PMID 37612540, 2023). "The variants identified in FTO, TAS2R, and NLRP14 genes were correlated with lifestyle-related factors for cancer installation, which are expected to be found in cases belonging to the LRLS group who are CRC-free." (PMID 37627102, 2023). "As a result, there are now many studies on the involvement of FTO in regulating cellular pathways in different types of cancer." (PMID 37007161, 2023). "Since FTO tends to be highly expressed in a variety of inflammatory conditions and cancers and is considered a potential therapeutic target." (PMID 39872548, 2023). "Our findings showed that FTO was somewhat linked, either positively or negatively associated with SRSF2 in 19 cancer types." (PMID 38015716, 2023). "Targeting dysregulated ALKBH5 and FTO is an appealing therapeutic approach for cancer in light of their essential functions in various malignancies." (PMID 37007161, 2023). "FTO plays a carcinogenic role in a variety of cancers, providing an opportunity to develop effective targeted therapeutics." (PMID 35879877, 2023). "Recent studies refined the FTO SNPs identification in relation to increased body mass index (BMI) and cancer." (PMID 37471425, 2023). "Although there exist FTO inhibitors used in cancer research, such as R-2-hydroxyglutarate (R-2HG) and FB23-2, it is still in the preclinical research stage." (PMID 37919739, 2023). "The m6A demethylase FTO was inversely correlated with TSs in most cancer type, suggesting that the RNA demethylation inhibits expression of telomerase components." (PMID 36239411, 2023). "FTO is a demethylase function as erasing role in the reversible methylation and has been reported to play an oncogenic role in various cancers." (PMID 37840133, 2023). "In line with the important roles FTO demethylase plays in cancer and other diseases, efforts have been made to develop small molecule inhibitors against FTO." (PMID 37612540, 2023). "First, we believe the role of FTO as an m6A eraser in NSCLC metastasis still needs to be verified due to the heterogeneity of different types of cancers." (PMID 37919739, 2023). "The m6A modification, especially through FTO overexpression has an oncogenic role in different cancer types such as EC." (PMID 36534072, 2023). "FTO is overexpressed in various human cancers to stimulate cancer cell metabolism, thereby inducing tumorigenesis and chemoresistance." (PMID 37626050, 2023). "FTO, the first described demethylase of m6A mRNA, has been reported as an oncogene in different types of cancers." (PMID 36874096, 2023). "We also discuss FTO’s mechanistic role in cancer and shed some light on m6A demethylase inhibitors as novel cancer-targeted therapies." (PMID 35409166, 2022). "Overall, our findings are consistent with a prior cytological study in PTC cells, even though they are contrary to the increased FTO expression in some other types of cancer as extrapolated from other investigations." (PMID 35721711, 2022). "For IDH mutant cancers, IDH inhibitors and FTO inhibitors can be combined to block the recovery of FTO functional activity caused by the reduction of R-2HG." (PMID 36226062, 2022). "As a key mediator enzyme of m6A modification, FTO exerts a vital function in promoting tumorigenesis and anti-tumorigenesis in various cancers, depending on its context." (PMID 35397614, 2022). "Our results emphasized the roles of FTO-regulated m6A modification in cancer progression, and also provided hints to develop therapeutic strategies against ESCC metastasis by targeting m6A modification and its related targets." (PMID 35524932, 2022).
cancer (continued). "Fat mass- and obesity-associated protein (FTO) was recently reported to participate in multiple tumorigenic processes including immune evasion in several malignant tumors, implying the therapeutic potential of FTO inhibition in treating multiple cancers." (PMID 35600848, 2022). "Another study suggested that m6A RNA modification catalyzed by enzymes including ALKBH5 and FTO had a fundamental role in the regulation of PI3K/Akt/mTOR signaling pathway in cancer." (PMID 35371987, 2022). "What is more, FTO suppresses the self-renewal of cancer stem cells in ovarian cancer by inhibiting 3’, 5’-cyclic adenosine monophosphate (cAMP) signaling." (PMID 35804965, 2022). "Among them, FTO promotes the metastasis and invasion of cancer cells through the FTO/miR-181b-3p/ARL5B signaling pathway." (PMID 36561529, 2022). "On account of its role in cellular metabolism, FTO is regarded as a potential factor in the pathogenesis of a variety of cancers by inducing chemoresistance and tumorigenesis." (PMID 35721711, 2022). "Subsequently, emerging evidence demonstrated that FTO is involved in a variety of cancers via an m6A-dependent mechanism." (PMID 35961973, 2022). "Owing to the complicated regulatory mechanisms, the FTO targets and their definitive roles in cancer remained limited." (PMID 35524932, 2022). "Conversely, knockdown of MIF in TA-MSCs reduced FTO expression and attenuated the cancer-promoting effect." (PMID 35794625, 2022). "Studies reviewed herein demonstrate that FTO is indeed an interesting druggable target in different human disorders, specifically cancers." (PMID 35409166, 2022). "Pathway analysis showed that ‘Pathways in cancer’ was significantly correlated with FTO-mediated m6A modification." (PMID 35090515, 2022). "The use of FTO inhibitors in conjunction with existing cancer therapies holds promising avenues for FTO-high expression tumors exhibiting resistance to cancer therapies as previously discussed." (PMID 35409166, 2022). "Along with the fat mass and obesity-associated protein (FTO), ALKBH5 is one of only two identified human m6A RNA oxidizing enzymes and is a potential target for cancer treatment." (PMID 35333330, 2022). "Due to the key roles of FTO in cancers, the identification of selective and effective inhibitors targeting FTO hold great therapeutic potential in carcinogenesis." (PMID 35422475, 2022). "The FTO protein plays a role in adipogenesis and cancer through the 6mA-dependent demethylase activity which affects various mRNA processing steps." (PMID 35923209, 2022). "On the other hand, increasing studies indicated that FTO is involved in pathogenesis and progression of various cancers." (PMID 35961973, 2022). "The targeted inhibition of FTO decreases body weight, suppresses cancer development, and inhibit the macrophage inflammatory response." (PMID 36263168, 2022). "As the first characterized m6A demethylase, FTO has been reported to regulate the tumorigenesis in different types of cancers." (PMID 35524932, 2022). "Several studies have shown that m6A methylation inhibitors, such as an inhibitor of FTO, can provide beneficial effects on the treatment of cancer." (PMID 35382893, 2022). "Overall, studies support FTO critical oncogenic roles in various cancer types as an m6A demethylase, given its abnormal expression and effect on many target genes." (PMID 35409166, 2022). "Intriguingly, targeting m6A erasers ALKBH5 or FTO has also shown beneficial effects to enhance ICI efficacy for cancer treatment." (PMID 36009465, 2022). "PDX models can be utilized as tools for personalized medicine strategies and cancer drug screening studies, such as testing FTO inhibitors in relation to its m6A-demethylase tumorigenic role." (PMID 35409166, 2022). "In OCs, m6A modifications mediated by FTO restrained cancer stem cells self-renewing process through inhibition of cAMP signaling." (PMID 36545327, 2022).